AR (androgen receptor)
Diseases named in the same sentence as AR in open-access papers (continued):
Sharing a sentence is not in itself a finding about the gene and the disease.
cancer (continued). "The clonal relationships of these populations were further probed by resequencing a panel of 400 cancer related genes, including the AR gene, in the diploid and aneuploid populations from 2007 and 2008 biopsies." (PMID 23372550, 2013). "The aim of the present study was to evaluate changes of androgen receptor (AR) expression quantitatively and to identify influences of AR on cancer related proteins in LNCap cell line by comparing es-LNCaP and ls-LNCaP." (PMID 23476140, 2013). "AR or AR/Src blockade by Casodex or S1 peptide impairs the biological responses challenged by EGF in these cancer cells." (PMID 24130806, 2013). "Enhanced AR activity is essential for cancer cell growth because PCa, in most cases, will regress in response to androgen removal therapy." (PMID 24970135, 2012). "Rearranged genes showed to be highly connected to well-known altered genes in cancer such as AR, RB1, MYC, and BRCA1." (PMID 22811706, 2012). "A study carried out in LNCaP cancer cells with Nano-Se suggested that Akt catalyzed androgen receptor (AR) phosphorylation was a key step for AR ubiquitination by Mdm2 and subsequent degradation by 26S proteasome." (PMID 22949823, 2012). "The cancer suppression function of Nano-Se consisted of at least two mechanisms, regulation of AR transcription and promotion of AR protein degradation." (PMID 22949823, 2012). "In the presence of androgens, endogenous and ectopically expressed AR directly associates with EGFR and decreases the activation of downstream PI3K signaling leading to cancer cell growth and survival." (PMID 23185449, 2012). "Androgen receptor (AR) signals have been suggested to contribute to bladder tumorigenesis and cancer progression." (PMID 22922989, 2012). "Direct effects of androgens on inducing breast cell proliferation and cancer via the AR are biologically impossible." (PMID 23273269, 2012). "A modest decrease in the antiapoptotic effect of epinephrine in cells where androgen receptor expression was reduced provides evidence that epinephrine reduces sensitivity of cancer cells to apoptosis." (PMID 22369514, 2011). "Androgen receptor, c-Myc and HIF-1α activity are associated with poor prognosis in many cancers, including PCa." (PMID 22087262, 2011). "The existence of P63+/AR-, CK14+/AR- and CD44+/AR- progeny indicates direct procurement of AR- malignant cancer trait." (PMID 21241512, 2011). "Most of the patients (220/365, 60%) with strong Wnt5a immunostaining in cancer tissues also exhibited intense AR staining." (PMID 22039506, 2011). "These sub-populations of AR- cancer cells were most likely to contribute directly to the androgen-independent tumors." (PMID 21241512, 2011). "A putative strategy to inhibit or diminish recruitment of coactivators to the receptor is to mimic the AR-Pax6 interaction in cancer cells." (PMID 21935435, 2011). "It has been well accepted that AR signaling contributes to carcinogenesis and cancer progression through regulating transcription of androgen-responsive genes." (PMID 22200028, 2011). "In 43.3% of carcinomas nuclear expression of AR was weak, while moderate to strong AR immunostaining was observed in only 9.3% of cases." (PMID 22191056, 2011). "Modification of AR signaling, in one form or another, is the dominant theme in HR cancer progression." (PMID 20406442, 2010). "Upregulation of the AR protein is perhaps the single most important pathway by which cancers achieve androgen "independence"." (PMID 20406442, 2010). "Basal markers are frequently lost in cancer and malignant glands display a luminal phenotype that includes abundant CK8/18 and AR expression, with loss of CK5 and p63." (PMID 19938015, 2010). "These cancers are often referred to as androgen independent, but most retain at least some dependence on the AR for survival." (PMID 20406442, 2010).
cancer (continued). "In the present study, we have shown that in vitro silencing of cystatin C by specific siRNA increased cancer cell invasion in cooperation with Erk2 and AR signalling." (PMID 19956729, 2009). "Recently, field effects based on epigenetic events, nuclear matrix alterations, androgen receptor immunoreactivity in the stroma surrounding cancer lesion have been discovered." (PMID 18974881, 2008). "For instance, growth of these cancer cells, mediated by their corresponding hormone receptors ERα and AR, is hormone-dependent." (PMID 18518979, 2008). "Our goal was to determine the mechanism of BPA action in cancer cells carrying BPA-responsive AR mutants." (PMID 18007998, 2007). "Our results demonstrate that carcinomas resistant to hormonal manipulations still depend on the expression of the androgen receptor for their development in vivo." (PMID 17925854, 2007). "The enzyme human steroid 5-α reductase type II (SRD5A2) and androgen receptor (AR) are critical mediators of androgen action, suggesting a potential role in hormonally related cancers." (PMID 11259089, 2001). "The role of AR signaling in cancer development is complex and multifaceted." (PMID 41486951, 2026). "We postulated that combined AR suppression and radiation may lead to increased intrinsic cancer cell signaling changes." (PMID 41542764, 2026). "Our findings across cancer types suggest that deactivation of AR in the TME reflects higher IFNγ signaling activity, which may indicate greater responsiveness to ICB therapy." (PMID 41486951, 2026). "Alongside YAP, androgen receptor (AR) is also gaining recognition for its role in cancer." (PMID 41517748, 2026). "In AR-overexpressing NPC-B13 cells, AR appeared to regulate thyroid transcription factor-1 (TTF-1, encoded by NKX2-1 gene) and its downstream target epidermal growth factor receptor (EGFR), thereby promoting cancer cell proliferation." (PMID 41633021, 2026). "Moreover, upregulation of KIFC1 in AR-TNBC increased cancer cell proliferation and promoted epithelial-mesenchymal transition (EMT), contributing to the aggressive characteristics of AR-TNBC." (PMID 40448099, 2025). "In addition, SeNPs achieve an anti-cancer effect by activating the Akt/Mdm 2 pathway to degrade the androgen receptor." (PMID 41227614, 2025). "The AR antagonists also showed efficacy in inducing cuproptosis in treating cancers." (PMID 40900810, 2025). "This was then used to target and induce degradation of androgen receptors (AR) in cancer cells." (PMID 39941922, 2025). "Of particular interest are cancers expressing both AR and NE markers (AR+/NE+ subtype)." (PMID 40493417, 2025). "Overall, the cellular positivity ranged from 5% to 95% with combined 2 + & 3 + intensities in 68% (17/25), 32% (8/25), and 84% (21/25) for ER, PR, and AR respectively, indicative of the higher rate and stronger expression of AR in HGSCA diagnostic cancer category." (PMID 40392873, 2025). "Overall, the research on sex hormone androgens and AR in these cancers is limited." (PMID 41228208, 2025). "Epithelial–mesenchymal transition (EMT) may constitute a mechanism by which AR exerts a direct impact on cancer progression." (PMID 41463239, 2025). "Furthermore, the identification of the LAR subtype has driven research into androgen receptor targeting as well as into the effects of PI3K inhibitors, which have been shown to make cancers more susceptible to DNA-damaging agents." (PMID 41463252, 2025). "This may indirectly argue for a functional role of stimulated AR in urothelial cancer cells with stronger in vivo effects on AR-positive cancers in male individuals with higher serum androgen levels than in females." (PMID 41463239, 2025). "Moreover, androgen receptor (AR)-mediated signaling upregulates telomerase expression in cancer cells." (PMID 41301813, 2025).
cancer (continued). "This study provides further evidence of the role of the androgen receptor (AR) and its truncated splice variants (SVs) in HCC and offers valine–niclosamide as a candidate therapeutic that addresses not only AR signaling in HCC but also other known pro-cancer signaling pathways." (PMID 40805231, 2025). "Additionally, determining the heterogeneity of AR isoform expression is crucial for appropriately applying AR inhibition in these cancers to ensure targeted and effective treatment." (PMID 41228208, 2025). "In hormone-dependent prostate cancer, Mito-LND-induced metabolic modulation might have additional potential by interfering with androgen receptor signaling, which plays a crucial role in regulating cancer metabolism." (PMID 39859224, 2025). "In another study involving 95 patients with high-risk (i.e., grade 3 and/or pT1) non-muscle-invasive bladder tumor, AR overexpression was associated with significantly better recurrence-free survival or cancer-specific survival." (PMID 40486871, 2025). "In recent years, the androgen receptor (AR) has become a crucial focus for the cancer therapy." (PMID 39927164, 2025). "We further compared NE1 and NE2 cells, finding that NE1 retained relative activation of the AR signaling axis and enrichment in cancer-promoting signaling pathways such as TNF-α and TGF-β, whereas NE2 showed upregulation in oxidative phosphorylation and mitochondrial metabolism." (PMID 41041045, 2025). "In addition, androgen/AR signaling has been observed to promote tumorigenesis in different cancer types, including OC." (PMID 40392873, 2025). "AR mediates sex differences in cancer progression by promoting CD8+ T cell exhaustion in males." (PMID 40438106, 2025). "RIPTACs are heterobifunctional molecules comprising a ligand that binds to a target protein in cancer cells, such as the AR, and a second ligand that binds to essential effector proteins (EPs) present in all cells whilst both these ligands are connected via a linker." (PMID 41374958, 2025). "HCC is a sexually dimorphic disease, and cancer progression is driven in part by AR activity." (PMID 40805231, 2025). "Additionally, many agonists and antagonists of AR have been developed and used in cancer treatment, and these methods can potentially be applied to cancers such as bladder, esophagus, head and neck, and stomach." (PMID 41228208, 2025). "In our cohort of patients with PCa, AR, FOXA1, MTOR, and MDM2 showed the highest rate of novel and pathogenic mutations, with 7, 3, 3, and 2, respectively, evidencing their relevance in this type of cancer." (PMID 41009328, 2025). "Also other factors were found to be valuable in prognosis of cancer recurrence such as: histologic growth pattern, ER expression, AR expression (its ratio with ER), Ki-67, and HER2." (PMID 40597870, 2025). "The cancer was strongly positive for ER, progesterone receptor (PR), and AR." (PMID 40729351, 2025). "AR blockade has now been tested in a number of other cancer types, with various results." (PMID 41228208, 2025). "Compared to current HCC therapies that offer only minimal improvements in overall survival, niclosamide offers promise as a cancer multitool compound due to its ability to decrease the AR/AR-SV protein and prevent rebound oncogenic signaling through its activity against NF-κB, STAT3, and KRAS." (PMID 40805231, 2025). "For instance, genomic profiling can reveal mutations in DNA repair genes like BRCA1/2 or alterations in the AR signalling pathway, which can guide the use of targeted therapies such as PARP inhibitors for BRCA-mutated cancers or next-generation AR signalling inhibitors." (PMID 40949469, 2025). "However, as PSMA was closely regulated by AR, its expression in PCa was heterogeneous within treated samples, leading to inaccuracies in molecular imaging and cancer surveillance." (PMID 40299363, 2025).
cancer (continued). "Moreover, we reintroduced LKB1 expression in PPL cancer cells, and demonstrated the restored AR phenotype by LKB1 expression, underscoring the role of LKB1 in regulating lineage plasticity." (PMID 39743630, 2025). "Hypoxia could induce the phenotype of cancer stem cells by regulating the Androgen receptor (AR)-miR-520f-3p-SOX9 cascade, which resulted in acquired resistance to sorafenib." (PMID 40264760, 2025). "Given its influence over various oncogenic mechanisms including the PI3K/AKT, EGFR, Src, and WNT pathways, AR dysregulation plays crucial roles in promoting the proliferation and progression of certain cancers such as prostate, breast, liver, and ovarian malignancies." (PMID 39744510, 2025). "In recent cancer studies, a central role has been described for AR signaling in CD8+ T cells." (PMID 40260919, 2025). "The blockade of AR has gained attention as a potential strategy for cancer therapy." (PMID 40303343, 2025). "DU-145 is a cell line characterized by no expression of AR and is more associated with a resistant cancer stage." (PMID 40126263, 2025). "It will also be important to explore the effects of androgen receptor inhibitors used in cancer therapy on APP pathways, and to determine whether the products of these pathways, including sAPPα or sAPPβ, contribute to disease development." (PMID 41614805, 2025). "Therefore, at least the recurrent cancers are potentially eligible for the anti-androgen/androgen receptor-antagonist therapy." (PMID 40392873, 2025). "Basic research indicates that the AR pathway interacts with DNA repair genes, with this pathway regulating the expression of several such genes; endocrine therapy can induce a "BRCAness" phenotype in cancer cells, thereby increasing their sensitivity to PARPI." (PMID 41079787, 2025). "This transformation, known as lineage plasticity, enables cancer cells to evade many conventional therapies, such as androgen receptor (AR)-targeted therapies and taxane-based chemotherapies, rendering them highly resistant and contributing to rapid disease progression." (PMID 41198652, 2025). "AR+/NE+ tumors, previously termed amphicrine carcinomas, express both AR and NE markers." (PMID 40493417, 2025). "However, this is far from curative, and it is important to gain a better understanding of AR biology, its effects on cancer growth/progression and, importantly, how it is involved in critical cancer cell intercellular communication pathways." (PMID 39858418, 2024). "The main relevance of AR expression in cancer comes from its role as a therapeutic target." (PMID 38790919, 2024). "The androgen receptor (AR) has been studied as an approach to cancer therapy." (PMID 37903548, 2024). "Targeting FOXM1 in AR-low TNBC may render cancer cells incapable of clustering their centrosomes and impair their ability to generate excess centrosomes." (PMID 39335162, 2024). "Therefore, developing therapeutic drugs targeting AR can serve as a new direction for preventing cancer progression." (PMID 39256355, 2024). "In this paper, the mechanism of action of AR active ingredients on cancer was sorted out." (PMID 39215362, 2024). "Among them, increased Androgen receptor expression has been considered as a favorable prognostic indicator in cancer patients and the poor prognosis of Cluster 2 in KIRC may be related to its lower expression." (PMID 39562162, 2024). "Currently, clinical trials are underway investigating therapeutic strategies for combining AR blockade with chemotherapy, targeted therapy, or immune checkpoint blockade in patients with advanced cancers (NCT04926181, NCT01974765, NCT03207529, NCT02684227, NCT02312557)." (PMID 38326303, 2024). "Importantly, YAP1, the AR, and the PSA were strongly associated with CD4+/CD8+ T cells in PC compared with other cancers (respectively)." (PMID 38540274, 2024).
cancer (continued). "We offer insights into AR-mediated immunosuppressive mechanisms, with the hope of translating preclinical and clinical evidence in gender oncology into improved outcomes in personalised, I/O-based cancer care." (PMID 38863718, 2024). "We validated these findings by Western blot and then moved to investigate if PQ and monensin could also downregulate ER-α and AR in other BC cancer cell lines." (PMID 38228924, 2024). "Using docetaxel in mCSPC is likely more efficacious at targeting AR-independent cancer cells early compared to its use in mCRPC since these cancer cells might have had opportunities to develop resistance." (PMID 39335158, 2024). "However, data on AR immunostaining in tumors are highly variable, especially in supposedly hormone-independent cancers." (PMID 38790919, 2024). "Typically, high AR activity correlates with more aggressive cancer types and poorer outcomes." (PMID 39296545, 2024). "Notably, in this model, we found that vaccination in combination with enzalutamide, an AR antagonist, suppressed these aggressive immune suppressive cancers and resulted in enhanced survival in comparison to control vaccinated and enzalutamide-treated mice." (PMID 39591176, 2024). "This cancer's growth and metastasis are driven in large part by the androgen receptor (AR)." (PMID 39114070, 2024). "Androgen receptor (AR) has been a key therapeutic target in cancers in recent years." (PMID 38965120, 2024). "Consequently, the primary objective of initial therapeutic hormonal interventions is to impede AR signaling via androgen deprivation therapy (ADT) either alone or in combination with AR-antagonists, leading to an initial regression of the cancer." (PMID 38589887, 2024). "Additionally, it has been reported that small molecule inhibitors can specifically target AR, making it the primary treatment target for advanced cancer." (PMID 38273392, 2024). "Furthermore, the cell survival signaling downstream of AR activation in these cancer models will need to be further elucidated." (PMID 39300603, 2024). "Furthermore, intratumoral androgen synthesis has been observed in CRPC, allowing cancer cells to produce their own androgens and sustain AR activation." (PMID 39184676, 2024). "Moreover, androgen/androgen receptor (AR) signaling has been found to promote tumorigenesis and metastasis in several cancer types, including AGCT." (PMID 39456756, 2024). "In addition, nonclassical androgen signaling through ZIP9 has also been reported to impact tumorigenesis, particularly in AR-null cancer cells." (PMID 38326303, 2024). "Additionally, nuclear localization of Hpa2 correlated with the levels of hormone receptors (ER, PR, AR), in agreement with the notion that hormone receptor-positive cancers grow more slowly than those that are hormone receptor-negative." (PMID 38519456, 2024). "Notably, AR regulates cancer cell metabolism to synthesize energy, such as promoting glycolysis, mitochondrial respiration, and fatty acid β-oxidation, as well as inducing cancer cell proliferation." (PMID 38625747, 2024). "It has a better affinity to the AR, thus increasing the rate of cancer development." (PMID 38238434, 2024). "The regulation of gene expression by NR is crucial for metabolism, cancer, neurological diseases, development, and immune responses, with key target genes, such as those for the GR, AR, PGR, ER, and PPARγ, governing specific pharmacological effects in particular tissues." (PMID 39065726, 2024). "Androgen receptor (AR) is one of the steroid hormone receptors which are essential transcription factors for mammalian physiology and are involved in the processes of cancer, reproductive system diseases, and musculoskeletal diseases." (PMID 39239655, 2024). "Alternatively, such cancers might respond to specific blockade of ERα while maintaining AR inhibition, perhaps also in the context of activation of signaling through ERβ." (PMID 39170834, 2024).